INS (insulin)
Diseases named in the same sentence as INS in open-access papers (continued):
Sharing a sentence is not in itself a finding about the gene and the disease.
retinopathy (333 papers, 2007 to 2026). "A risk of intensified insulin regimen in MS is worsening or rapid development of retinopathy or nephropathy." (PMID 41560719, 2026). "Theoretically and traditionally, intensified multiple insulin injection therapy is an approach that will cause rapid improvement in metabolic status but also greatly increase the risk of developing retinopathy." (PMID 39170998, 2024). "Forty-seven percent of patients with EOD and 23% of those with LOD were classified into the severe insulin-deficient group representing the highest risk of retinopathies." (PMID 38028250, 2023). "It is possible that Asian individuals have more severe impairment of insulin secretion, which is reported to be linked to retinopathy, even independently of HbA1c." (PMID 37452207, 2023). "Although several studies have reported retinopathy worsening following insulin injection, the mechanism underlying such a development has remained unclear." (PMID 34337073, 2021). "The Stress syndrome prototype was associated with impaired insulin sensitivity and retinopathy as indicators of neurodegeneration." (PMID 33670473, 2021). "The retinopathy signs were associated with increased glucose and 2-h insulin levels in OGTT as well as systolic blood pressure, triglycerides and lower HDL cholesterol." (PMID 33091029, 2020). "Important finding was that 30 min and 1-h post-load glucose and 2-h insulin levels were independently associated with retinopathy." (PMID 33091029, 2020). "After adjustment with systolic blood pressure, 30 min glucose, 1-h glucose and 2-h insulin were independently associated with retinopathy." (PMID 33091029, 2020). "Our findings show the potential role of these increased post-load glucose and insulin levels as risk factors for retinopathy development." (PMID 33091029, 2020). "Only 30 min glucose, 1-h glucose and 2-h insulin were associated with retinopathy signs, after controlling with systolic blood pressure." (PMID 33091029, 2020). "After adjustment with systolic blood pressure, only 30 min glucose, 1-h glucose and 2-h insulin levels were associated with retinopathy signs." (PMID 33091029, 2020). "The retinopathy signs were significantly associated with increased 30 min, 1-h and 2-h glucose levels and 2-h insulin level in an OGTT." (PMID 33091029, 2020). "In patients without retinopathy at enrollment, the 3-year risk of developing retinopathy was reduced by 75 % in the intensive insulin treatment group compared to the conventional treatment group." (PMID 27847639, 2016). "For example, the reduced risk of retinopathy associated with intensive insulin therapy persisted for up to 10 years in the observational follow-up EDIC study, despite the convergence of HbA1c levels in the intensive and conventional groups (HbA1c∼8.0%)." (PMID 20456170, 2010). "AID achieves higher time in range than multiple daily injections and standard insulin pumps and therefore may pose a higher risk of retinopathy." (PMID 41560719, 2026). "This phenomenon may be associated with findings that insulin users in Taiwan have significantly higher risk of developing diabetic complications such as retinopathy." (PMID 37196125, 2023). "The insulin-deficient subgroup showed the highest proportions of retinopathy (24%)." (PMID 37402743, 2023). "Continuous subcutaneous insulin infusions using an insulin pump may reduce the risk of complications such as retinopathy and peripheral neuropathy." (PMID 32582034, 2020). "Additionally, in T1D patients, the use of insulin repressed genes of angiopathy and retinopathy, and macrophage gene expression was associated with GDM." (PMID 24885568, 2014). "Similarly, SGLT2i was associated with a lower risk of sight-threatening retinopathy than sulfonylureas in all subgroups of variables, and the interaction was significant in the insulin subgroup (AHR, 0.76; 95% CI, 0.61-0.94; P = .001) (eTable 4 in Supplement 1)." (PMID 38117497, 2023).
retinopathy (continued). "Loss of insulin signaling through insulin resistance, loss of β2-adrenergic receptor input, and production of the anti-apoptotic inhibitors, TNFα, could lead to retinal cell death associated with retinopathy." (PMID 23894672, 2013). "The present study further confirmed that, among insulin-treated patients with T2D, GLP-1 RA therapy was associated with a significantly lower risk of sight-threatening retinopathy compared with DPP-4 inhibitors." (PMID 41011236, 2025). "Before PSM, SGLT2i initiators were younger, with a longer disease duration, higher BMI and HbA1c, worse lipid profile, more prevalent retinopathy, and more concomitant use of insulin, but higher baseline eGFR and lower pre‐index date eGFR slope." (PMID 40600449, 2025). "HbA1c monitoring, retinopathy and foot screening, insulin initiation/titration, acute inpatient care." (PMID 41158567, 2025). "Anti-diabetic medication showed a significant association with DR severity (P = 0.039), where participants on insulin had a higher likelihood of severe retinopathy compared to those on oral hypoglycemic agents." (PMID 39867069, 2024). "People who were overtreated were less likely to have retinopathy and be on medications such as metformin, sulphonylureas, insulin, and DPP4i." (PMID 38387535, 2024). "The current study demonstrated significant retinopathy in with patients receiving insulin treatment compared to metformin in T2DM." (PMID 39495998, 2024). "In our study, a significant increase in retinopathy was detected in diabetic patients managed by insulin therapy." (PMID 39295783, 2024). "It was demonstrated that the STZ-induced DR rats treated with insulin jointly with oral delivery of the curcumin-laden double-headed nanoparticles displayed ameliorated diabetic cataracts and retinopathy compared to those treated with insulin alone." (PMID 38892648, 2024). "the chance of proliferative retinopathy in both insulin and protaminated groups was significantly more than oral medication group." (PMID 37828117, 2023). "The chance of proliferative retinopathy in diabetic patients who had received insulin and protaminated insulin wasn’t significantly different from oral group." (PMID 37828117, 2023). "The patients from the reported family were treated by OAD or insulin, and patients with longer time of the disease showed retinopathy and peripheral polyneuropathy." (PMID 35592779, 2022). "Several potential confounders were present in this study; the insulin group had a significantly longer duration of DM as well as higher proportions of severe retinopathy and higher proportions of PRP laser at baseline." (PMID 35227220, 2022). "From our data, it appears that patients with an A1c > 8.0 and requiring insulin seem to have an increased the chance of retinopathy (p < 0.0001)." (PMID 33541295, 2021). "In extremely preterm infants, high early postnatal plasma glucose levels and signs of insulin insensitivity were associated with lower IGF1 levels and increased retinopathy of prematurity severity." (PMID 33004691, 2020). "Subjects with retinopathy signs had significantly higher fasting and post-load glucose values, 2-h serum insulin level in an OGTT, systolic blood pressure, triglycerides and lower HDL cholesterol (p<0.05)." (PMID 33091029, 2020). "At P12, streptozotocin-treated mice with oxygen-induced retinopathy had significantly lower insulin plasma levels." (PMID 33004691, 2020). "Patients with retinopathy showed significantly higher levels of triglycerides, basal insulin, and HOMA-IR." (PMID 31029141, 2019). "Other endpoints include HbA1c, weight, LDL cholesterol, insulin requirement, progression of retinopathy, endothelial function and frequency of hypoglycaemia." (PMID 27935183, 2017). "Other potential relative risk factors reported in the literature including increased levels of HbA1c in serum, treatment with insulin/insulin and oral hypoglycemic agents, retinopathy, prolonged walking, living alone, and low literate education." (PMID 28969714, 2017).
retinopathy (continued). "The significant univariate factors and possible confounding factors used in stepwise logistic regression included age, UACR, insulin usage, and retinopathy stage." (PMID 26955641, 2016). "At the time of the study, two of the patients with retinopathy were taking 1 unit/kg insulin and the remaining two were taking 1.2 unit/kg insulin." (PMID 26899627, 2016). "Retinopathy is identified in a group of patients who were younger yet had a longer known duration of DM with worse glycemic control and higher rates of insulin use." (PMID 26089953, 2015). "CrHis prevents the changes in the expressions of GLUT1, GLUT3 and insulin and the level of MDA in the retina tissue, confirming the protective effect of CrHis supplementation against the retinopathy caused by STZ." (PMID 25652875, 2015). "After the patients were subdivided according to severity of retinopathy, age, sex, and concentrations of fasting blood glucose, HbA1c, and insulin, the HOMA-IR indexes were similar for each subgroup." (PMID 24895642, 2014). "In a large study, diabetic subjects receiving IGF-I for 12 weeks experienced major decreases in insulin requirements, but side effects included edema, jaw pain, tachycardia and worsening of retinopathy." (PMID 25339185, 2014). "On the other hand, insulin seems to have neuroprotective effects and specifically in the retina reduces retinal cell apoptosis, glial activation, and VEGF upregulation, and its deficiency is associated with retinopathy progression." (PMID 39998445, 2025). "In addition, while the chance of non-proliferative retinopathy in the insulin group had a significant difference compared to the oral treatment group, it was not significant in the protaminated insulin group." (PMID 37828117, 2023). "The reasons for this may partly be explained by excluding people using GLP-1 analogue and/or insulin and people with retinopathy, the first mentioned because of other aspects of the PanGut study investigating the incretin effect." (PMID 37593120, 2023). "Furthermore, the chance of developing non-proliferative retinopathy in insulin group was 5.3-folds (P = 0.012) But it wasn’t significant in protaminated insulin group." (PMID 37828117, 2023). "HK2 is a predominant HK isoform in insulin-sensitive tissues including the retinopathy." (PMID 35096809, 2021). "However, just like in the current study, retinopathy occurred more often in the group that underwent insulin treatment." (PMID 32268561, 2020). "Limitations of this study include its observational nature and, despite the large number of patients included compared to earlier similar studies, the lack of power to analyze the association between insulin use and retinopathy." (PMID 33306685, 2020). "People with the highest FG-CV in the first 5-year interval showed an increased risk of insulin initiation, retinopathy, macrovascular complications and mortality independent of mean glycemia, classical risk factors and medication use." (PMID 31830993, 2019). "A prospective study with seven years of follow-up identified that being a malewas a risk factor for amputation among patients with diabetic feet, together with otherfactors such as long time since diagnosis, high glycated hemoglobin, retinopathy and theuse of insulin." (PMID 27533270, 2016). "Statistical analysis of the differences between clinical manifestations and laboratory data between the two patient groups revealed significant findings for the following parameters: age (p = 0.005), UACR (p = 0.001), insulin usage (p = 0.05), and stage of retinopathy (p < 0.001)." (PMID 26955641, 2016). "Self-reported confidence levels in diagnosing retinopathy and the use of intravenous insulin." (PMID 18419804, 2008).
retinopathy (continued). "The authors of this analysis suggested that this phenomenon in the SUSTAIN 6 study might be attributed to a rapid reduction in HbA1C during the initial 16 weeks in patients treated with Semaglutide and insulin, particularly those already suffering from retinopathy with poor glycemic control." (PMID 38542021, 2024). "However, a slightly higher proportion of patients in group 2 using insulin may contribute to increased retinopathy, necessitating tighter glucose control to achieve lower HbA1c percentages." (PMID 38842591, 2024). "In addition, obese and overweight children with retinopathy had significantly higher values of triglycerides (90.20 vs. 105.57 mg/dl, p = 0.04), basal insulin (12.97 vs. 17.20 mUI/ml p = 0.02), and HOMA-IR (2,76 vs. 3,37, p = 0.04) than patients without retinopathy." (PMID 37033164, 2023). "Additionally, intensive insulin therapy was also shown to slow the progression of DR by 54% and reduce progression to proliferative or severe non-proliferative retinopathy by 47% in participants that entered the study with mild retinopathy." (PMID 36498694, 2022). "However, the removal of insulin users, or subjects with retinopathy, did not alter the significance of the associations (data not shown)." (PMID 34206644, 2021). "To assess whether IGF1 supplementation can promote revascularization and therefore decrease neovascularization in oxygen-induced retinopathy in the setting of disturbed insulin signaling, we injected recombinant IGF1 starting at P12 when revascularization of the avascular retina begins." (PMID 33004691, 2020). "This meta-analysis from 20 RCT analysing 18,599 T2D patients showed no benefit of insulin vs. hypoglycaemic drugs or vs. diet/placebo on all-cause mortality, cardiovascular mortality, micro and macro vascular complications, except for retinopathy requiring photocoagulation." (PMID 27391319, 2016). "Therefore, continuous insulin delivery resulting in a slow and step-by-step improvement of metabolic control is an acceptable method of improving metabolic status without increasing the risk of rapidly proliferative retinopathy." (PMID 39170998, 2024). "Therefore, improvement in insulin sensitivity might be the defining factor, implicating the protective effect of the 12Ala variant against disease proliferation in individuals with T2DM who have retinopathy." (PMID 23559865, 2013). "For example, in patients with retinopathy at baseline in the DCCT, intensive insulin therapy slowed progression by 54%." (PMID 20456170, 2010). "One case report discussed standard insulin pump therapy with manual dose intensification and noted no retinopathy after 2.5 years, but growth data were lacking." (PMID 41560719, 2026). "Patients with DR had worse glycemic control (mean glycated hemoglobin: 7.67 ±1.07 vs. 6.61 ±0.74 in those without retinopathy, p<0.001) and a higher need for insulin (33% vs. 8.3%, p=0.002)." (PMID 40625489, 2025). "Retinopathy was detected in 125 out of 366 patients with HbA1C of 9 % or more, 107 of whom were using insulin therapy, whereas 18 were not, with a p-value of 0.005." (PMID 39295783, 2024). "Moreover, smoking history, insulin, and ACEI/ARB use were also more common in patients with retinopathy." (PMID 37323224, 2023). "We found that PR and RI were associated with increased vascular rigidity of the retinal artery in patients with early retinopathy who were taking insulin as compared with those not taking insulin." (PMID 34283877, 2021). "In the nationwide population-based cohort, the analysis of insulin as a protective factor against severe retinopathy of prematurity found a large but not significant effect after controlling for confounding factors." (PMID 33306685, 2020). "Analytical models were also carried out in a dataset without patients undergoing insulin treatment (n = 27) or patients with microvascular diabetic complications (e.g., retinopathy, n = 4), which might affect inflammation or cortisol secretion." (PMID 34206644, 2021).
retinopathy (continued). "The lack of complete normalization by insulin treatment offers the potential that these proteins may play a role in the ‘metabolic memory’ observed clinically in retinopathy pathogenesis." (PMID 21249158, 2011). "Insulin initiation in non-insulin-dependent DM (NIDDM) patients with constantly administrated blood glucose levels and poor patient monitoring worsen the condition and may prompt prognosis in severe non-proliferative retinopathy and early proliferative retinopathy." (PMID 38357071, 2024).